IL17A (interleukin 17A)
Diseases named in the same sentence as IL17A in open-access papers (continued):
Sharing a sentence is not in itself a finding about the gene and the disease.
psoriasis (continued). "In order to further explore the relationship between hub genes and the mainstream pathogenic mechanism of psoriasis, we analyzed the relationship between these genes and LCN2/IL17A." (PMID 33613635, 2021). "By this unique mechanism, brodalumab binds IL-17RA and inhibits signaling of IL-17 isoforms, in addition to IL-17A and IL-17A/F, providing high efficacy, fast onset of action, and high probability of complete psoriasis clearance." (PMID 34201664, 2021). "We had found L-THE regulated chemokine signaling pathway and IL-17A signaling pathway associated genes, such as CXCL2, CCL3 and CCL4 in skin tissues from mice with psoriasis." (PMID 34381369, 2021). "Psoriasis is a chronic inflammatory, immune-mediated disease which is induced by many pro-inflammatory cytokines, such as IL-17A, TNF-a, IL-22 and IL-23." (PMID 34992498, 2021). "Second, to exclude the possibility that MCPIP3 regulates IL-17A response in a T-cell-intrinsic manner, we used an recombinant IL-23-induced psoriasis model, which sidesteps initial activation by myeloid cell and activates T cells directly via IL-2355." (PMID 34215755, 2021). "In psoriasis mice models, dermal overexpression of IL-17A induced systemic endothelial dysfunction, vascular oxidative stress, and arterial hypertension." (PMID 34201664, 2021). "Biologic agents targeting IL-17A or IL-17RA have been demonstrated to have considerable clinical impact in the treatment of psoriasis, and this further proves the vital role of IL-17A in psoriasis." (PMID 35186952, 2021). "While IL-17A-producing CD4+ TRM also exist in healthy skin, the enrichment of CD8+ TRM producing IL-17A in the epidermis is one of the characteristics of psoriasis." (PMID 34501272, 2021). "Regardless of the persistence of this population by various treatments in psoriasis, many of the current and upcoming therapeutics in clinical practice presumably exert an indirect influence on cutaneous IL-17A-producing TRM." (PMID 34501272, 2021). "The effect of gut microbiota on the distal skin inflammation seems to be achieved by changing the secretion of cytokines, especially IL-17A, to induce systemic inflammation over-activation in psoriasis." (PMID 34881280, 2021). "In our study, serum IL-17A levels were significantly higher in patients with early onset psoriasis (223.78 ± 435.21 ng/mL) than those with late onset group (31.69 ± 12.14 ng/mL), respectively (P = 0.020)." (PMID 33356031, 2021). "As anti-TNF and anti-IL-17A treatments were applied and both cytokines play a key role in the pathophysiology of psoriasis, the search was focused on these two biological pathways." (PMID 34746142, 2021). "Diese Begleiterkrankungen können durch systemische Entzündungsprozesse verstärkt werden, die im Zusammenhang mit der Psoriasis auftreten und durch Interleukin-17A (IL-17A) gesteuert werden." (PMID 34417630, 2021). "psoriasis by accelerating the release of chemokines which contribute to the recruitment of IL-17A-producing immune cells and neutrophils." (PMID 34712239, 2021). "Stimulation with IFN-γ/IL-17A/IL-22 cytokine combination induced changes in the mRNA expression profile in human keratinocytes that mimic psoriasis-like transcriptional signature." (PMID 33986690, 2021). "Secukinumab is a fully human monoclonal antibody that selectively neutralizes IL-17A, a cytokine fundamental to the development of psoriasis." (PMID 34578893, 2021). "So far, using keratinocyte monolayers and an in vitro 3D psoriasis model, we observed that IL-17A induces IL-36 cytokines and that a feedback loop between IL-17 and IL-36 cytokines provokes and maintains psoriasis pathology." (PMID 34440590, 2021). "In psoriasis, IL-17A is pointed out as the most important mediator, which is supported by the effectiveness of its blockade in patients." (PMID 34778294, 2021).
psoriasis (continued). "Of note, a pilot study on an animal model, concerning IL-17A involved both in the pathogenesis of psoriasis and HT inflammatory model signaling, indicated IL-17 antibodies as a potential treatment target for HT and associated end-organ dysfunction." (PMID 34445769, 2021). "For example, Il-17A inhibitors can significantly improve the symptoms, signs, physical function, and quality of life of patients with AS and psoriasis." (PMID 35310892, 2021). "In experimental studies, with psoriasis models, IL-17A shown to be a mediator of thrombotic events and vascular dysfunction." (PMID 34540858, 2021). "When keratinocytes are stimulated by TNF-α, IFN-γ, IL-22 and IL-17A, they can express the inflammatory marker proteins related to psoriasis, such as chemokines and proinflammatory cytokines." (PMID 34456715, 2021). "IL-17A, another important biologic target of psoriasis, plays a vital role in the pathogenesis of both psoriasis, and atherosclerotic plaques that accumulating evidence supports a beneficial influence of its agonists on related cardiometabolic comorbidities." (PMID 34803716, 2021). "As IL-17A produced by γδT cells is essential for the development of IMQ-induced psoriasis, we next investigated the effects of MabE on the IL-17A-producing γδT cells." (PMID 33836731, 2021). "The decrease in IκBζ expression due to SKSI-0412 causes decreased nuclear translocation, which subsequently causes decreased expression of the psoriasis-associated genes (DEFB4 and S100A7) in IL-17A-induced keratinocytes." (PMID 34445513, 2021). "Canonical pathway analysis showed the role of IL17A in psoriasis, the role of IL17F in inflammation in airways, and chronic obstructive pulmonary disease (COPD) signaling pathways were severely affected by SARS-CoV-2 infection." (PMID 34582497, 2021). "Perhaps of relevance to this study is that the CD1A inflammatory response is mediated by Th17 cells and that in vivo anti-IL17A treatment has been observed to ameliorate skin inflammation in a mouse psoriasis model." (PMID 34673799, 2021). "IκBζ is an important regulator in the development of psoriasis and an important transcriptional activator that mediates the downstream effects of IL-17A." (PMID 34445513, 2021). "In psoriasis, IL-23 is overproduced by dendritic cells and keratinocytes, and this stimulates Th17 cells within the dermis to make IL-17A and IL-22." (PMID 34441010, 2021). "In our psoriasis model, immigration of neutrophils occurred after injection of both IL-17A + IL-36γ, but also in response to IL-36γ alone, albeit to a lesser extent." (PMID 34440590, 2021). "Several therapeutic modalities currently used for psoriasis treatment, such as anti-IL-23p19 or anti-IL-17A antibodies, retinoids, topical vitamin D3, DMF, and narrow-band UVB, can restore defective Tregs." (PMID 34501328, 2021). "We then investigated the effect of curcumol on viability and proliferation of NHEK cells stimulated with a combination of proinflammatory cytokines characteristic for psoriasis (IL-1α, IL-17A, IL-22, oncostatin M, and TNF-α; mix M5)." (PMID 34314383, 2021). "IL-23 is considered to be a key cytokine in psoriasis that promotes the proliferation of skin-resident T helper cells (especially Th17 and Th22) and the release of IL-17A and IL-22." (PMID 33801280, 2021). "Psoriasis is the first indication approved for clinical usage of anti-IL17A monoclonal antibody, and so far, psoriasis is still considered the very first indication for research of most IL17A antagonists." (PMID 33509093, 2021). "MiR-766-3p was upregulated in both HaCaT cells treated with the psoriasis-related cytokine pool (IL-17A, IL-22, IL-1 alpha, oncostatin M, and TNF-alpha) and tissues." (PMID 34992498, 2021). "IL-17A and its upstream regulator IL-23 are two key molecules in the pathogenesis of psoriasis, and approaches that specifically target this pathway showed great clinical responses." (PMID 34575956, 2021).
psoriasis (continued). "Nfkbiz knockout mice have shown resistance to imiquimod (IMQ) and IL-23-induced psoriasis, but IL-17A knockout mice have shown only partial resistance to the IMQ-induced psoriasis phenotype." (PMID 34445513, 2021). "The IL-17 cytokine family consists of 6 members, A–F, but only two have a pathogenetic role in psoriasis, IL17-A, and IL-17F." (PMID 34829740, 2021). "IκBζ is an important regulator of several psoriasis-related genes, including IL-17A downstream genes such as DEFB4, S100A7, and IL-6." (PMID 34445513, 2021). "It is currently believed that IL17A is the core driving factor of the pathogenesis of psoriasis, and LCN2 plays an indispensable role in this disease by acting as an antibacterial peptide and as a trigger for neutrophil activation in psoriasis." (PMID 33613635, 2021). "This has been further supported by a recent clinical study with psoriasis patients, in which improvement in vascular and myocardial function has been observed after IL-17A inhibition." (PMID 34201664, 2021). "Innate immune cells, such as type 3 innate lymphoid cells, γδT cells, or invariant natural killer T cells, also produce IL-17A, and are involved in the pathogenesis of psoriasis." (PMID 34501328, 2021). "IMQ, a ligand of TLR-7/8, induces psoriasis-like dermatitis in mouse mimicking human psoriasis pathogenesis and systemic inflammation, including elevated levels of IL-23/IL-17A-Th17 axis pro-inflammatory cytokines and chemokines 34-36." (PMID 33391503, 2021). "In psoriasis, IL-17-producing T helper cells (Th17) are central in the pathogenesis and Th17-related cytokines such as IL-17A, IL-17F and IL-22, together with TNFα, drive epidermal hyperplasia." (PMID 34616394, 2021). "Compared with severe psoriasis, mild psoriasis was characterized by higher IL-17A expression in psoriatic lesion, which is consistent with the alteration of RORC in our study." (PMID 33681365, 2021). "In the present study, we have provided evidence for psoriasis-like changes in human keratinocytes as a result of IFN-γ/IL-17A/IL-22 stimulation." (PMID 34834106, 2021). "Anti-p40 is an approved drug for psoriasis treatment, which can inhibit IL-23A-induced IL-17A production through binding to the p40 subunits of IL-23 and IL-12." (PMID 34354596, 2021). "The feature that broadly blocks IL-17A, IL-17F, IL-17C and IL-17E enables IL-17RA to rapidly improve the clinical and histological features of psoriasis." (PMID 34975883, 2021). "IL-17A + IL-36γ-treated mice showed typical signs of psoriasis, including hyperparakeratosis, as well as an acanthosis with spongiosis and dermal oedema." (PMID 34440590, 2021). "The tumor necrosis factor-alpha (TNF-α)/IL-23/IL-17A axis plays a key role in induction and progression of psoriasis; thus, biological drugs against TNFα/IL-23/IL-17A have good therapeutic efficacy." (PMID 33499346, 2021). "When IL-17F was studied in mice models of psoriasis, results showed that IL-17F-producing cells were more abundant than those producing IL-17A and IL-22." (PMID 34201664, 2021). "Clinical studies in psoriasis patients indicated that both blockade of IL-23 as well as IL-17A are effective." (PMID 34552583, 2021). "This is also undermined by the strong psoriasis-like skin phenotype upon transgenic expression of IL-17A, a key cytokine produced by TH1 cells, under the control of the keratin-14 promoter in mice." (PMID 34440590, 2021). "This study aimed to establish an IL-17A and IL-36γ intradermal ear injection model of psoriasis to elucidate the role of both cytokines in the complex pathogenesis of the disease." (PMID 34440590, 2021). "Several skin-constituting factors have been reported to support the development and persistence of IL-17A-producing TRM in psoriasis." (PMID 34501272, 2021).
psoriasis (continued). "The present study examines the expression of the genes IL-10, IL-17A, IL-17RA, IL-23A and IL-23R in the skin and peripheral blood of patients with psoriasis and of healthy people, to identify potential factors regulating the development of psoriatic lesions." (PMID 34945130, 2021). "The pivotal psoriasis IL-17A signaling up-regulates the cellular cholesterol concentrations, leading to its accumulation in keratinocytes." (PMID 34445769, 2021). "Since dexamethasone blocked the overall inflammation process, IL17A is likely to play a partial role in the pathogenesis of IMQ-induced psoriasis." (PMID 33509093, 2021). "The results of this non-targeted metabolomic analysis indicate that treatment with IL-17A mAbs can not only ameliorate psoriasis lesions but also restore dysregulated lipid metabolism to normal levels in psoriasis patients." (PMID 33602246, 2021). "Secukinumab is a monoclonal antibody against IL-17A that is FDA-approved for the treatment of psoriasis." (PMID 33948920, 2021). "The impact of the IL‐17A inhibitor secukinumab on adipose tissue and cutaneous inflammation in patients with moderate‐to‐severe psoriasis is being explored prospectively in the ongoing ObePso‐S trial (NCT03055494)." (PMID 34803716, 2021). "Hyperforin also suppressed the typical psoriasis-like inflammatory responses and the infiltration of IL-17A+ cells in dermal γδ T cells of IMQ treated Tcrd−/− mice transferred with γδ T cells." (PMID 34025642, 2021). "By addition of the psoriasis cytokines from the in vitro experiments (IL-17A, TNF-α, IL-22, 20 ng/mL each), an inflammatory milieu typical for psoriasis was simulated." (PMID 33801280, 2021). "After initial activation by myeloid cells, subsequent IL-17A production by T cells further accelerates psoriasis pathogenesis." (PMID 34215755, 2021). "IL-17A inhibitors are well established and known as efficient and safe for the treatment of psoriasis, rheumatoid arthritis, and inflammatory bowel diseases." (PMID 33432451, 2021). "In conclusion, intradermal injection of IL-17A + IL-36γ into the ear pinnae of mice provides an in vivo model to investigate psoriasis, which mimics both histological and gene expression aspects of the disease." (PMID 34440590, 2021). "IL-17A plays a pivotal role in the pathophysiology of psoriasis, as it has prominent effects on epithelial cells, including keratinocytes." (PMID 34201664, 2021). "Experimental models of skin inflammation identified IL-17A/F-producing γδ T cells as necessary and sufficient to trigger psoriasis-like plaque formation in IL-23- or Immiquimod-induced models." (PMID 34335608, 2021). "Case reports have shown that patients with psoriasis treated with IL-17A antagonists, including secukinumab and ixekizumab, showed relatively mild disease or were asymptomatic when they were infected with SARS-CoV-2." (PMID 34575667, 2021). "IL-17A antibodies are already approved for the treatment of psoriasis and severe adverse effects on the immune status have, thus far, not been apparent." (PMID 34772416, 2021). "Of note, we found that NAMPT expression is strongly reduced by Secukinumab, an anti-IL-17A antibody successfully used in the treatment of psoriasis patients, suggesting its implication in disease pathogenesis." (PMID 34202251, 2021). "IL-17A has been shown to be up-regulated in psoriasis lesions and is central to psoriasis pathogenesis." (PMID 34616394, 2021). "Particularly, ixekizumab, a humanized‐monoclonal immunoglobulin‐G 4 antibody, specifically binding IL‐17A, demonstrated strong efficacy in threating recalcitrant psoriasis." (PMID 34436817, 2021). "The interaction between IL-17A secreted by TH17 cells and epidermal keratinocytes plays a key pathogenic role in triggering psoriasis." (PMID 34044769, 2021). "While former studies used IL-23 to induce psoriasis in mouse models, we went a step further in the cytokine cascade by injecting IL-17A and IL-36γ." (PMID 34440590, 2021).
psoriasis (continued). "We also showed that secukinumab, an anti-IL-17A antibody licensed for the treatment of psoriasis, can be effective in the treatment of patients with severe CSU." (PMID 33801296, 2021). "IL-17A recognition by IL-17R expressed on keratinocytes plays a crucial role in the psoriasis development and neutrophil infiltration in experimental models." (PMID 33510592, 2021). "Clinical studies and targeted therapies have demonstrated that the cytokines TNF, IL-23, and IL-17A have pivotal roles in psoriasis pathogenesis." (PMID 34215755, 2021). "Treatment with agomir-miR-340 alleviates the severity of IMQ-induced psoriasis in mice by directly targeting IL-17A." (PMID 33968012, 2021). "In this study, we investigated the effects of PSORI-CM02 on angiogenesis in the skin and the underlying mechanisms in IL-17A-stimulated human umbilical vein endothelial cells (HUVECs) and a murine model of imiquimod (IMQ)-induced psoriasis." (PMID 33995368, 2021). "IL-6 and IL-22, which are potent STAT3 activators, are known for their synergistic action with IL-17A in the pathogenesis of psoriasis." (PMID 34445513, 2021). "On the contrary, both TNFis (except for etanercept) and anti-IL17A agents produced consistent cutaneous responses (i.e., Psoriasis Area Severity Index (PASI) response) compared to placebo." (PMID 34211394, 2021). "Recently, IL-17A inhibitors were proved to be novel bDMARDs for several autoimmune diseases, including psoriasis, rheumatoid arthritis, and inflammatory bowel disease." (PMID 33432451, 2021). "Topical application of SHR168442 in Vaseline exhibited excellent efficacy in the imiquimod-induced and IL-23-induced psoriasis-like skin inflammation mouse models and correlated with the reduction of Th17 pathway cytokines, IL-6, TNFα and IL-17A." (PMID 33911101, 2021). "Over the last decade, the biological blockade of IL-17A has improved the symptoms of psoriasis significantly." (PMID 34445513, 2021). "Specifically, L-THE can significantly decrease the levels of IL-23 and chemokines, and attenuate the IMQ-induced psoriasis like skin inflammation by inhibiting the activation of NF‐κB and IL-17A signaling pathway." (PMID 34381369, 2021). "Autoimmune signature in psoriasis seems driven by local and systemic Th17 patterns, expressing IL-17A, IL-22, and IFN-γ." (PMID 34697538, 2021). "The inhibitory effect of anti-IL-17A on psoriasis plays an important role in the early clinical, histopathological and molecular treatment of psoriasis." (PMID 34134787, 2021). "For example, ibrutinib, a Bruton’s tyrosine kinase inhibitor, suppresses IMQ-induced psoriasis-like skin inflammation in mice by downregulating IL-17A and IL-23 expression." (PMID 34955833, 2021). "Our present study aimed to establish a murine intradermal ear injection model to investigate the effects of IL-36γ and IL-17A in the pathomechanism of psoriasis." (PMID 34440590, 2021). "Further, several additional agents directly targeting IL-17A or its receptor have all been approved for use in psoriasis." (PMID 33749662, 2021). "Psoriasis patients exhibit enhanced circulating levels of IL-6, IL-18, IL-17A, IFN-γ, TNF, IL-1β, IL-27 and IL-29." (PMID 34068473, 2021). "While the IL-17A-treated mice showed only slight gene expression effects, mice injected with IL-17A + IL-36γ exhibited significant upregulations in all selected psoriasis-relevant gene sets." (PMID 34440590, 2021). "We evaluated serum levels of IL-17A and other cytokines, including IL-22 and IL-19,18 from the psoriasis molecular signature." (PMID 34643650, 2021). "Topical application of sodium butyrate to imiquimod-induced psoriasis-like dermatitis in mice increased IL-10 and Foxp3 transcripts and reduced inflammation and IL-17A transcripts." (PMID 34501328, 2021).